BIVM (basic, immunoglobulin-like variable motif containing)
Synonyms: FLJ20159
Tractability: No criterion of Open Targets' tractability assessment is met for any kind of drug.
Gene: Protein-coding gene on chromosome 13 (102,799,110 to 102,841,748, forward strand). Ensembl gene ENSG00000134897.
Subcellular location: Cytoplasm; Nucleus
Subcellular location (Human Protein Atlas): Nucleoplasm
Gene Ontology:
Molecular function: protein binding; DNA endonuclease activity; single-stranded DNA binding
Cellular component: extracellular region; nucleoplasm; nucleus; cytoplasm
Genetic constraint (gnomAD): Loss-of-function variants: 31 observed, 62.53 expected, observed/expected ratio (o/e) 0.5, 90% interval 0.37 to 0.67. The upper end of that interval is the gene's LOEUF score, 0.67, which puts it in group 2 of 6, group 1 being the genes least tolerant of losing a copy. Missense variants: 526 observed, 623.91 expected, observed/expected ratio (o/e) 0.84, 90% interval 0.78 to 0.91. Synonymous variants: 189 observed, 217.8 expected, observed/expected ratio (o/e) 0.87, 90% interval 0.77 to 0.98.
Homologues: Orthologues: chimpanzee ERCC5 (97% identical), macaque BIVM (97% identical), dog BIVM (96% identical), guinea pig Bivm (95% identical), rat Bivm (88% identical), mouse Bivm (87% identical), tropical clawed frog bivm (68% identical), zebrafish bivm (54% identical), dog ERCC5 (5% identical), mouse Ercc5 (4% identical), rat Ercc5 (2% identical).
Diseases named in the same sentence as BIVM in open-access papers:
BIVM is named in the same sentence as 2 diseases in open-access papers, as found by Europe PMC text mining. Sharing a sentence is not in itself a finding about the gene and the disease. The quoted sentences say what the papers report.
ciliopathies (1 paper, 2023). "Study found BIVM is expressed at the base of cilia and is a key gene in ciliopathies." (PMID 36757497, 2023).
cancer (1 paper, 2021). A tumor composed of atypical neoplastic, often pleomorphic cells that invade other tissues. "Of the coexpressed genes, NAXD and BIVM also displayed hazard ratios comparable to that of ERCC5 in LGG, although their association with cancer has not been reported." (PMID 34966786, 2021).